BAG4 (BAG cochaperone 4)
Description:
Inhibits the chaperone activity of HSP70/HSC70 by promoting substrate release (By similarity). Prevents constitutive TNFRSF1A signaling. Negative regulator of PRKN translocation to damaged mitochondria.
Synonyms: BAG-4; SODD
Tractability: Antibody: its Gene Ontology location is reachable by antibodies, with high confidence. PROTAC: ubiquitination databases record sites on it; its protein half-life has been measured.
Gene: Protein-coding gene on chromosome 8 (38,176,533 to 38,213,301, forward strand). Ensembl gene ENSG00000156735.
Subcellular location: Cytoplasm
Pathways (Reactome):
Disease: Signaling by FGFR1 in disease; Signaling by plasma membrane FGFR1 fusions
Cellular responses to stimuli: Regulation of HSF1-mediated heat shock response
Signal Transduction: TNF signaling
Gene Ontology:
Molecular function: protein binding; RNA binding; ubiquitin protein ligase binding; adenyl-nucleotide exchange factor activity; protein-folding chaperone binding
Biological process: cellular response to tumor necrosis factor; negative regulation of establishment of protein localization to mitochondrion; negative regulation of apoptotic process; protein folding; protein stabilization; cellular response to epidermal growth factor stimulus; positive regulation of actin filament polymerization; positive regulation of cell adhesion; positive regulation of fibroblast migration; positive regulation of phosphatidylinositol 3-kinase/protein kinase B signal transduction; positive regulation of stress fiber assembly; protein localization to plasma membrane; ruffle assembly
Cellular component: cytosol; nucleus; plasma membrane; membrane; cytoplasm
Genetic constraint (gnomAD): Loss-of-function variants: 25 observed, 49.56 expected, observed/expected ratio (o/e) 0.5, 90% interval 0.37 to 0.7. The upper end of that interval is the gene's LOEUF score, 0.7, which puts it in group 2 of 6, group 1 being the genes least tolerant of losing a copy. Missense variants: 511 observed, 561.42 expected, observed/expected ratio (o/e) 0.91, 90% interval 0.85 to 0.98. Synonymous variants: 205 observed, 218.84 expected, observed/expected ratio (o/e) 0.94, 90% interval 0.83 to 1.05.
Homologues: Orthologues: chimpanzee BAG4 (100% identical), macaque BAG4 (98% identical), rabbit BAG4 (89% identical), pig BAG4 (87% identical), rat Bag4 (86% identical), mouse Bag4 (85% identical), guinea pig BAG4 (80% identical), tropical clawed frog bag4 (32% identical), zebrafish bag4 (30% identical), Drosophila melanogaster stv (22% identical). Paralogues in human: BAG3 (22% identical), BAG5 (11% identical).
Diseases named in the same sentence as BAG4 in open-access papers:
BAG4 is named in the same sentence as 28 diseases in open-access papers, as found by Europe PMC text mining. Sharing a sentence is not in itself a finding about the gene and the disease. The quoted sentences say what the papers report.
breast carcinoma (6 papers, 2013 to 2025). "Additionally, previous studies have reported that BAG4 is associated with poor prognosis in various tumor types, including pancreatic, ovarian and breast cancers." (PMID 40870378, 2025). "Overexpression of BAG4 has been reported in pancreatic, ovarian and breast cancers, as well as in acute lymphoblastic leukemia and colon cancer." (PMID 40870378, 2025).
colorectal cancer (6 papers, 2017 to 2025). A primary or metastatic malignant neoplasm that affects the colon or rectum. "For example, circ_005169 exerted oncogenic function via sponging miR-145 and increasing the expression of E2F5, BAG4, and FMNL2 in colorectal cancer cells." (PMID 28219405, 2017). "Some researchers provide evidences that circ_001569 acts mechanically as a miRNA sponge to inhibit miR-145 activity, and subsequently up-regulates miR-145 targets E2F5, BAG4 and FMNL2 to promote cell proliferation and invasion in CRC (colorectal cancer)." (PMID 28279183, 2017). "Likewise, hsa-circ-001569 may promote the proliferation and invasion of colorectal cancer cells by sponging miR-145 and subsequently upregulating the expression of E2F5, BAG4, and FMNL2." (PMID 31821171, 2019).
lung carcinoma (4 papers, 2015 to 2025). "Furthermore, in lung cancer, BAG4 has been implicated in promoting proliferation, invasion, metastasis and drug resistance, functioning within the PI3K/PDK1/AKT and RAF/MEK/ERK signaling pathways." (PMID 40870378, 2025). "BAG4, a protein transcribed from a gene at 8p11.23 with a role in the inhibition of apoptosis, has been shown to transform breast cells and may have functional implications for lung cancer, being commonly coamplified with FGFR1 and NSD3." (PMID 36902501, 2023).
acute lymphoblastic leukemia (3 papers, 2023 to 2025). Leukemia with an acute onset, characterized by the presence of lymphoblasts in the bone marrow and the peripheral blood. "Research has indicated that BAG4 is associated with invasive characteristics of a variety of human tumor types, including pancreatic, breast, acute lymphoblastic leukemia, gastric, and colon cancers." (PMID 40515636, 2025). "Studies on acute lymphoblastic leukemia (ALL) have also demonstrated that BAG4 is overexpressed in ALL, where it plays a significant role in biological processes such as apoptosis and chemotherapy sensitivity." (PMID 40870378, 2025).
colon cancer (3 papers, 2017 to 2025). "In colon cancer tissues, hsa_circ_001988 expression reduced and hsa_circ_001569 negatively correlated with miR-145 as a sponge by attenuating BAG4, E2F5, and FMNL2 expressions." (PMID 36313671, 2022). "For example, DIEXF gene (in the list of colon cancer) and BAG4 gene (in the list of leukemia) act in the apoptosis process." (PMID 29563929, 2017).
pancreatic cancer (3 papers, 2014 to 2025). "BAG4 has been found to be overexpressed in pancreatic cancer and positively correlated with ANXA7, HSP70 and BCL-2." (PMID 40870378, 2025).
breast tumours (1 paper, 2016). "In breast tumours the 8p11-12 amplicon is broad resulting in increased copy number of FGFR1 and of multiple neighboring genes and studies have shown that some of these neighboring genes, for example WHSC1L1, BAG4 and DDHD2, can be oncogenic." (PMID 26905262, 2016).
cervical cancer (1 paper, 2025). A primary or metastatic malignant neoplasm involving the cervix. "Notably, BAG2 expression was significantly reduced in cervical cancer, while no significant changes were observed in other BAG family members (BAG1, BAG3, BAG4, BAG5, and BAG6), suggesting a unique role for BAG2 in cervical cancer." (PMID 40364789, 2025).
leukemia (1 paper, 2017). A malignant (clonal) hematologic disorder, involving hematopoietic stem cells and characterized by the presence of primitive or atypical myeloid or lymphoid cells in the bone marrow and the blood. "Also, key genes of leukemia data set were BAG4, ANKHD1-EIF4EBP3, PLXNC1, and PCDH9 genes, and the accuracy and precision were 100 and 95.24, respectively." (PMID 29563929, 2017).
lung adenocarcinoma (1 paper, 2010). A carcinoma that arises from the lung and is characterized by the presence of malignant glandular epithelial cells. "BAG-1, BAG-2, BAG-5 might be the potential protective factors while BAG-4 is possible risk factor of lung adenocarcinoma." (PMID 20959066, 2010).
Sepsis (1 paper, 2014). Sepsis is defined as life-threatening organ dysfunction caused by a dysregulated host response to infection. "Based on previous research, it was shown that homozygous mutant mice for Bag4 have enhanced cytokine responses and increased IL-6 production following TNF challenge i.e. septic shock (Kp is a major pathogenic cause of sepsis)." (PMID 25283706, 2014).
cancer (12 papers, 2010 to 2025). A tumor composed of atypical neoplastic, often pleomorphic cells that invade other tissues. "Although the existing literature suggests that BAG4 promotes cell proliferation, migration and invasion in various cancers, its clinical significance and underlying molecular mechanisms in AML remain unclear." (PMID 40870378, 2025). "The findings indicate that USP14 stabilizes BAG4, which restricts Parkin recruitment to mitochondria and consequently suppresses mitophagy in cancer cells." (PMID 40316942, 2025). "Knockdown of USP14 or treatment with a USP14-specific inhibitor (IU1) led to significantly increased BAG4 ubiquitination levels in cancer cells, implying that USP14 normally functions to deubiquitinate BAG4 and prevent its degradation." (PMID 40316942, 2025). "Overexpression of USP14 caused a dose-dependent increase in BAG4 protein, while knockdown of USP14 in cancer cells resulted in a marked reduction in BAG4 protein levels." (PMID 40316942, 2025). "Results from CCK8 and EDU assays revealed that silencing USP14 significantly suppressed cancer cell proliferation, while BAG4 overexpression rescued this effect." (PMID 40316942, 2025). "Although BAG4 is believed to be involved in the pathology of various cancer types, its specific mechanisms remain inadequately defined." (PMID 40870378, 2025). "The findings revealed that BAG4 expression varies across different cancer types and is notably elevated in AML." (PMID 40870378, 2025). "Targeting the USP14/BAG4/PRKN axis to enhance mitophagy shows promise for improving cancer treatment efficacy." (PMID 40316942, 2025). "Promotes NK cell activity in an HSP70/Bag-4 surface-positive exosome-dependent manner for the immune elimination and cytotoxicity of cancer cells." (PMID 38994941, 2024). "miR-145-5p influences cancer invasiveness via the inhibition of BAG cochaperone 4 (BAG4) and formin-like 2 protein (FMNL2)." (PMID 32610706, 2020). "Similarly, colony formation assays indicated that USP14 knockdown impaired the clonogenic ability of cancer cells, which was restored by BAG4 overexpression." (PMID 40316942, 2025). "In summary, this study uncovers a novel regulatory axis involving USP14 and BAG4 in cancer cells." (PMID 40316942, 2025). "Among them, BAG1, BAG3, and BAG4 (also named SODD) may be associated with BCL-2 and correlated with the development processes of some cancers." (PMID 37107587, 2023). "In conclusion, the data indicate that BAG4 is crucial in USP14-driven tumorigenesis and chemosensitivity in CRC, significantly influencing cancer progression and oxaliplatin treatment response." (PMID 40316942, 2025). "The study underscores the therapeutic promise of targeting the USP14/BAG4/PRKN axis to boost mitophagy and increase cancer cell sensitivity to chemotherapy, especially oxaliplatin." (PMID 40316942, 2025).
tumor (12 papers, 2013 to 2025). "BAG4 has been identified as a tumor marker for multiple malignancies and is implicated in tumor progression and drug resistance." (PMID 40870378, 2025). "Similar to other oncogenes, BAG4 upregulation typically inhibits tumor cell apoptosis, whereas its downregulation is associated with reduced tumor growth." (PMID 40870378, 2025). "High expression of USP14 and BAG4 was associated with poor overall survival, highlighting their potential as markers for aggressive tumor behavior." (PMID 40316942, 2025). "Later, same research team demonstrated that the expression of HSP70 and co-chaperone BCL2-associated athanogene 4 (BAG4) on tumor-derived exosomes enhances migration and cytolytic activity of NK cells." (PMID 34917098, 2021). "The upregulation of BAG4 is generally associated with the inhibition of apoptosis in tumor cells, while its downregulation may lead to a reduction in tumor development." (PMID 40870378, 2025). "The study found that USP14 and BAG4 were significantly overexpressed in tumor tissues compared to normal tissues, whereas PRKN expression was markedly reduced." (PMID 40316942, 2025). "In summary, our study highlights the role of USP14 in promoting tumor progression by regulating the BAG4/PRKN-mediated mitophagy pathway." (PMID 40316942, 2025). "Consistent with our in vitro data, knockdown of USP14 significantly suppressed tumor growth, while BAG4 overexpression abrogated this inhibitory effect." (PMID 40316942, 2025). "While the potential impact of BAG4 on tumor formation was analyzed through bioinformatics approaches, validation is necessary for the correlations between BAG4 expression, AML prognosis, and immune cell infiltration." (PMID 40870378, 2025). "This process highlights a key mechanism through which USP14 controls BAG4 protein stability in CRC (MSI-H), offering insights into the USP14-BAG4 axis’s role in tumor biology and suggesting a potential therapeutic target for disrupting BAG4." (PMID 40316942, 2025). "USP14 stabilizes BAG4 via K48-deubiquitination, hindering Parkin-mediated mitophagy, which results in the accumulation of damaged mitochondria and fosters tumor progression." (PMID 40316942, 2025). "Tumor derived HSP70/bag-4 surface positive exosomes can stimulate NK cells to release granzyme B, which in turn triggers tumor cell apoptosis." (PMID 37823027, 2023). "The mechanistic studies via quantitative analysis of global proteome in xenograft tumours revealed that some metastasis-associated proteins, including S100A4, MARCKSL1 and BAG4 were increased in ELL(C595A) xenograft tumours compared to the control tumours." (PMID 27009366, 2016). "Further analysis across different tumor grades demonstrated a clear association between protein expression and disease severity: USP14 and BAG4 levels increased progressively with higher tumor grades, while PRKN expression decreased as the tumor grade advanced." (PMID 40316942, 2025). "We hypothesize that USP14 regulates tumor growth and response to chemotherapy through interactions with BAG4 and PRKN, thereby influencing mitophagy and apoptosis pathways." (PMID 40316942, 2025). "circ_001569 was proved to sponge miR-145, finally increasing the expression level of miR-145 downstream target E2F5, Bag4, and FNL2 and promoting tumor proliferation and invasion." (PMID 35783017, 2022). "The profiling data showed that 7 apoptosis-related genes were concordantly > twofold downregulated in recurrent tumor samples compared with the expression in paired primary tumor samples, including AKT1, BAG4, BCL2A1, BFAR, CARD6, CASP8 and TNFRSF21." (PMID 34488754, 2021). "Mechanically, circ_001569 acts as a miRNA sponge to directly inhibit miR-145, and subsequently up-regulates miR-145 targets E2F5, BAG4 and FMNL2 to exert its tumor promoting function in CRC cells." (PMID 27058418, 2016). "The upregulations of S100A4, MARCKSL1, BCAM, BAG4, IPO4 and CPSF7 in pHAGE-ELL(C595A) tumours were confirmed." (PMID 27009366, 2016).
tumor (continued). "The significant clinical relevance of USP14, BAG4, and PRKN are proved in tumor tissues." (PMID 40316942, 2025). "This suggests a potential role of USP14 and BAG4 in promoting tumor progression, while PRKN may act as a tumor suppressor in CRC (MSI-H)." (PMID 40316942, 2025). "The study highlights the USP14/BAG4/PRKN axis as a critical pathway in CRC (MSI-H), suggesting that targeting USP14 could inhibit tumor progression and improve chemotherapeutic outcomes." (PMID 40316942, 2025). "Thus, circ_001569 acts as a miRNA sponge to directly combine with miR-145, and subsequently up-regulates miR-145 targets E2F5, BAG4 and FMNL2 to exert its tumor promoting function in CRC cells." (PMID 27058418, 2016). "Statistical analysis revealed increased expression of FGFR1 neighboring genes on the 8p12 amplicon (BAG4, LSM1 and WHSC1L1) in FGFR1 amplified tumours, suggesting a broad rather than focal amplicon and raises the potential for codependencies." (PMID 26905262, 2016).
bacterial infection (1 paper, 2014). "One of the interesting candidate genes was found within Kprl2 QTL, Bag4 (BCL2-associated athanogene 4), which mediates cell-cell and cell-extracellular matrix interactions and this complex plays a role in host response to bacterial infection." (PMID 25283706, 2014). "Kprl2 contains the candidate gene Bag4 (BCL2-associated athanogene 4), which mediates cell-cell and cell-extracellular matrix interactions and this complex plays a role in host response to bacterial infection." (PMID 25283706, 2014).
BAG4 also shares sentences with these, for which no sentence is quoted: melanoma (5 papers); acute myeloid leukemia (1); adenocarcinoma (1); diabetes (1); diabetic retinopathy (1); esophageal adenocarcinoma (1); fibrosarcoma (1); gastric cancer (1); infection (1); liver cancer (1); lung squamous cell carcinoma (1); ovarian carcinoma (1); septic shock (1); tuberculosis (1).